HIF1A (hypoxia inducible factor 1 subunit alpha)
Diseases named in the same sentence as HIF1A in open-access papers (continued):
Sharing a sentence is not in itself a finding about the gene and the disease.
ovarian diseases (2 papers, 2025 to 2026). "Our findings indicate that PAE reduces ovarian reserve through HDAC1-linked epigenetic silencing of Usp9x, exacerbating HIF1α/NOBOX pathway dysfunction, thereby informing aspirin's gestational safety and future interventions for fetal-origin ovarian disorders." (PMID 41524225, 2026). "Based on these preliminary observations, we are aim to further explore the potential role of the HIF‐1α/HIGD1A axis in the pathogenesis of hypoxia‐related ovarian diseases, such as ovarian torsion and ovarian tissue transplantation." (PMID 40801481, 2025).
ovarian endometriosis (2 papers, 2019 to 2025). A non-neoplastic disorder characterized by the growth of endometrial tissue in the ovaries. "Increased expression of HIF-1α is well-known in endometriotic lesions, particularly in ovarian endometriosis." (PMID 41013698, 2025). "Taken together, the data provided evidence that the autophagy process occurred during ovarian endometriosis, and elevated expression of HIF‐1α and lncRNA‐MALAT1 may be involved in the pathological process." (PMID 30324652, 2019). "In the present study, we found that the expression of lncRNA‐MALAT1 was remarkably up‐regulated and positively correlated with the expression of HIF‐1α and autophagy marker LC3 in ovarian endometriosis tissue samples." (PMID 30324652, 2019).
pelvic organ prolapse (2 papers, 2017 to 2025). Abnormal descent of a pelvic organ resulting in the protrusion of the organ beyond its normal anatomical confines. "The purpose of this study is to evaluate the expression of hypoxia-inducible factor-1α (HIF-1α) in women uterosacral ligament tissues with pelvic organ prolapse and women with normal uterine support structures and illuminate its relationship with apoptosis." (PMID 29230415, 2017). "Hypoxia may contribute to the pathological process of pelvic organ prolapse by increasing apoptosis via activating HIF-1α signaling pathway." (PMID 29230415, 2017). "Recent studies have reported a significantly elevated expression of hypoxia-inducible factor 1-alpha (HIF-1α) in the vaginal wall tissues of patients with pelvic organ prolapse (POP), indicating that hypoxic injury may play a significant role in the pathogenesis of POP." (PMID 41223182, 2025). "The expressions of HIF-1α and BNIP3 in the uterosacral ligaments were significantly higher in patients with pelvic organ prolapse than in control group." (PMID 29230415, 2017).
periapical granuloma (2 papers, 2022 to 2025). Chronic nonsuppurative inflammation of periapical tissue resulting from irritation following pulp disease or endodontic treatment. "Several previous studies have investigated the expression of HIF-1α in radicular cysts and periapical granulomas,2, 8, 9and demonstrate their hypoxic nature." (PMID 39657933, 2025). "Many of the periapical granulomas examined were positively immunolabeled for HIF-1α both in the cytoplasm and nucleus of the cells, with a higher level of positivity noted in the cytoplasm than in the nucleus." (PMID 39657933, 2025). "We observed a high expression of HIF-1α protein in both radicular cysts and periapical granulomas, with significantly greater expression in radicular cysts compared with periapical granulomas." (PMID 39657933, 2025). "In contrast, periapical granulomas also express HIF-1α in the cytoplasm and nucleus, although its expression is more pronounced in the cytoplasm." (PMID 39657933, 2025). "Increased expression of ATG5-ATG12 and activating phosphorylation of AMPK, accompanied by augmented levels of hypoxia inducible factor 1 subunit alpha, HIF1α, has been observed in periapical granulomas." (PMID 35992149, 2022). "Chi-square test revealed a significant difference in the expression of HIF-1α and VEGF between radicular cysts and periapical granuloma (chi-square test = 8.906,p = 0.031; chi-square test = 10.401,p = 0.015, respectively)." (PMID 39657933, 2025). "The chi-square test revealed a highly significant difference in the expression of HIF-1α and VEGF between radicular cysts and periapical granulomas (chi-square test = 8.906,p = 0.031; chi-square test = 10.401,p = 0.015, respectively)." (PMID 39657933, 2025). "There is high expression of both HIF-1α and VEGF throughout the odontogenic epithelium and connective tissue of the radicular cyst and periapical granuloma." (PMID 39657933, 2025). "Spearman's correlation test showed a significant correlation between HIF-1α and VEGF in total samples of radicular cysts and periapical granulomas (rho = 0.385,p = 0.005)." (PMID 39657933, 2025). "Spearman's correlation test showed a significant correlation between HIF-1α and VEGF in the total samples of both radicular cysts and periapical granulomas (rho = 0.385,p = 0.005)." (PMID 39657933, 2025). "This study aimed to evaluate the expression levels of HIF-1α and VEGF in radicular cysts and periapical granulomas, thereby contributing to the understanding of their potential significance in the differential diagnosis and treatment of these lesions." (PMID 39657933, 2025). "Both HIF-1α and VEGF are more highly expressed in radicular cysts than in periapical granulomas." (PMID 39657933, 2025). "VEGF expression was absent in 1 (4.2%), weak in 6 (25.0%), mild in 9 (37.5%), and strong in 8 (33.3%) cases; nevertheless, in periapical granulomas, HIF-1α expression was absent in 8 (29.6%), weak in 6 (22.2%), mild in 9 (33.3%), and strong in 4 (14.8%) of the cases." (PMID 39657933, 2025). "In the light of high expression of HIF-1α and VEGF in radicular cysts and periapical granulomas, one could suggest evaluating the nonsurgical treatment of these lesions using anti-HIF-1α and anti-VEGF therapy." (PMID 39657933, 2025).
Pleural effusion (2 papers, 2022 to 2024). The presence of an excessive amount of fluid in the pleural cavity. "Based on the similar characteristics of pleural and peritoneal cavity, tumor cells in pleural effusion were also positive for HIF-1α and GLUT-1 and had a relatively low Ki-67 index." (PMID 36620569, 2022).
pneumococcal infection (2 papers, 2017 to 2020). Infections with bacteria of the species streptococcus pneumoniae. "Overall, these data demonstrate improvement of BBB function by HIF-1α inhibition with echinomycin, leading to improved clinical symptoms and survival post-pneumococcal infections." (PMID 32529267, 2020). "We also unexpectedly found that HIF-1α mediates PAFR-independent pneumococcal infection in unstimulated respiratory cells." (PMID 28278175, 2017). "Expression of HIF-1α in unexposed respiratory cells inhibits basal pneumococcal infection via PAFR-independent mechanisms." (PMID 28278175, 2017). "The effect of WF on respiratory cell reactive oxygen species production, HIF-1α expression, and pneumococcal infection was determined using flow cytometry, HIF-1α knockdown and overexpression, and pneumococcal infection assays." (PMID 28278175, 2017). "We therefore sought to assess i) whether constitutive PAFR expression is increased in nasal epithelial cells from welders, ii) whether the effect of WF on pneumococcal infection is generalisable to WF with differing compositions, and iii) the role of oxidative stress induced HIF-1α in this response." (PMID 28278175, 2017). "We found that nasal PAFR expression is significantly increased in welders compared with controls and that WF significantly increased reactive oxygen species production, HIF-1α and PAFR expression, and pneumococcal infection of respiratory cells." (PMID 28278175, 2017). "In brain ECs (bEnd5 cells), pneumococcal infection with clinical S. pneumoniae isolates (D39, TIGR4) led to dramatic reduction of oxygen levels within minutes of infection, leading to hypoxia that persisted for hours resulting in HIF-1α activation at RNA and protein levels in brain ECs." (PMID 32529267, 2020).
pneumothorax (2 papers, 2010 to 2013). Abnormal presence of air in the pleural cavity. "Collectively, these results show that spontaneous pneumothorax in smokers is associated with lung macrophage oxidative stress and the orchestrated induction of the antioxidant proteins HO-1, BVR and H-ferritin, probably via an HIF-1α pathway." (PMID 20526373, 2010).
polyp (2 papers, 2021 to 2022). A usually exophytic mass attached to the underlying tissue by a broad base or a thin stalk. "HIF-1α expression in SM of patients with CRSwNP is significantly increased compared to SM of healthy controls and the HIF-1α level in polyp tissues is positively associated with IL-17A production and neutrophilic inflammation." (PMID 36292050, 2022).
primary biliary cholangitis (2 papers, 2021). Primary biliary cholangitis (PBC) is a chronic and slowly progressive cholestatic liver disease of autoimmune etiology characterized by injury of the intrahepatic bile ducts that may eventually lead to liver failure. "Of interest, this study also reported a nuclear HIF-1α-positive stain in macrophages, hepatocytes and fibroblasts in liver specimens obtained from patients with primary biliary cholangitis (PBC) and primary sclerosing cholangitis (PSC)." (PMID 34359934, 2021). "UDCA, a licensed agent for primary biliary cholangitis, antagonized hypoxic HCC cell–induced angiogenesis and inhibited the upregulation of HIF-1α, VEGF, and IL-8." (PMID 34975472, 2021).
pulmonary embolism (2 papers, 2020 to 2025). The obstruction of the pulmonary artery or one of its branches by an embolus, sometimes associated with infarction of the lung. "Our experiments indicate that in the acute pulmonary embolism combined with shock model, the TLR4/NF-κB/HIF-1α signaling pathway is activated, which might stimulate the upregulation on the expression of downstream Gal-3, and the release of inflammatory factors such as IL-6 and TNF-α." (PMID 40666114, 2025).
pulmonary tuberculosis (2 papers, 2017 to 2019). A bacterial infection that affects the lungs and is caused by Mycobacterium tuberculosis. "In the current work, it was shown that during M. tb infection, both in infected U937 cells and in human tissue of pulmonary tuberculosis, Hif-1α obviously increased." (PMID 28835201, 2017). "Histologically, in lung tissues of patients with pulmonary tuberculosis, it was also found that the expression of Hif-1α was increased." (PMID 28835201, 2017).
Q fever (2 papers, 2022 to 2024). A bacterial infection caused by Coxiella burnetii. "We recently showed that HIF1α hampers replication of the obligate intracellular pathogen Coxiella burnetii which causes the zoonotic disease Q fever." (PMID 35755850, 2022). "Indeed, a recent study has shown that hypoxia-induced HIF-1α-response in Mφs limited the replication of C. burnetiid without affecting its viability, thus allowing it to persist chronically and this may be linked to the development of chronic Q fever." (PMID 39119289, 2024). "Thus, HIF1α might play an important role in the induction of C. burnetii persistence, and consequently, the development of chronic Q fever." (PMID 35755850, 2022).
renal sclerosis (2 papers, 2013 to 2018). "A large of evidence indicates that HIF-1α is a key cytokine of renal sclerosis in hyperglycemic conditions." (PMID 30420600, 2018). "There is accumulating evidence revealing that hypoxia-inducible factor (HIF)-1α is a key regulator of renal sclerosis under diabetic conditions." (PMID 24278186, 2013). "The antagonistic key factor against hypoxia is HIF-1α and it is a key regulator of renal sclerosis under diabetic conditions." (PMID 24278186, 2013).
respiratory infections (2 papers, 2022 to 2023). "Further, PIO attenuated EtOH-induced HIF-1α, which could provide a novel therapeutic strategy in the treatment of alcohol use disorders in the lung and decrease susceptibility to respiratory infections." (PMID 35634337, 2022). "In agreement with the results of those studies, our findings indicate that respiratory infection induces respiratory epithelial permeability by activating HIF-1α–VEGFA signaling." (PMID 36916939, 2023).
retinal (2 papers, 2019 to 2021). "The suppression of AQP-4 prevents the binding of HIF1α to the VEGF promoter, thus reducing hypoxia induced-retinal damage." (PMID 34681190, 2021).
retinal detachment (2 papers, 2020 to 2022). An eye emergency condition which may lead to blindness if left untreated. "The rationale for this declaration is that experimental BRVO (induced by laser occlusion of the retinal vasculature) causes extensive serous retinal detachment after 1 day, yet hypoxia—whether delineated by pimonidazole or HIF-1α–was only observed in the inner retina of BRVO retinas." (PMID 36467607, 2022). "Equipped with the knowledge that retinal detachment did not cause a reduction in outer retinal pO2 that was sufficient to cause pimonidazole staining, HIF1α accumulation or upregulation of HIF target genes, we investigated expression of COX IV in photoreceptor inner segment mitochondria." (PMID 36467607, 2022). "Given that retinal detachment does not cause photoreceptor hypoxia, as evidenced by the lack of pimonidazole staining or HIF1α accumulation, we investigated whether there is a marked loss of mitochondrial COX IV within inner segments, as occurs in the detached cat retina." (PMID 36467607, 2022).
rosacea (2 papers, 2025). A chronic erythematous skin disorder that affects the face. "In rosacea patients, the increased levels of IL-6 correlate with ROS production and activation of the hypoxia-induced factor HIF-1α, and both effects are mediated through the IL-6/JAK/STAT3 pathway." (PMID 40006535, 2025).
Salmonella Infections (2 papers, 2021 to 2023). Infections with bacteria of the genus SALMONELLA. "Importantly, inhibition of EGFR and HIF1α restored both proteomics and metabolomics changes caused by Salmonella infection." (PMID 33868285, 2021). "Our in vitro and in vivo data strongly suggests that HIF-1α plays a crucial role in regulating Salmonella infection." (PMID 33868285, 2021). "One of the downstream signaling of EGFR involves mTOR and HIF-1α axis, which was also found to be significantly affected by Salmonella infection in THP-1 cells." (PMID 33868285, 2021). "To understand the immunological response mediated by EGFR and HIF-1α during Salmonella infection, we infected the mice with S. Typhimurium and treated them with Gefitinib or Acriflavin." (PMID 33868285, 2021). "Consistently, Gefitinib treatment of S. Typhimurium-infected mice showed recovery associated with inhibition of HIF-1α, further emphasizing the critical role EGFR-HIF-1α axis regulating Salmonella infection in vivo." (PMID 33868285, 2021).
SARS-CoV infection (2 papers, 2022 to 2025). "HIF-1α’s high expression promotes and aggravates inflammatory responses during the SARS-CoV infection." (PMID 41157602, 2025).
sickle cell disease (2 papers, 2025). Sickle cell anemias are chronic hemolytic diseases that may induce three types of acute accidents: severe anemia, severe bacterial infections, and ischemic vasoocclusive accidents (VOA) caused by sickle-shaped red blood cells obstructing small blood vessels and capillaries. "Hypoxic conditions known to affect pulp homeostasis also promote pain in conditions such as sickle cell disease; several mechanisms such as sensitization of nociceptive TRPV1 receptors or algogenic action of Hypoxia Induced Factor 1‐alpha (HIF1a) can be hypothesized." (PMID 40574609, 2025).
silicosis (2 papers, 2023 to 2025). Silicosis is a respiratory disease caused by breathing in (inhaling) silica dust. "ROS further activate the inflammasome through MAPK3 and phosphorylate Ser276 of p65 NF-κB and Ser641 and Ser643 of HIF-1α, to promote the development of silicosis." (PMID 37381044, 2023).
sleep disorder (2 papers, 2022 to 2023). A change from the patient's baseline sleeping pattern, in the hours slept and/or an alteration/dysfunction in the stages of sleep. "For instance, as one of the types of sleep disorder, Obstructive Sleep Apnea (OSA) could increase ROS/HIF-1α 'related oxidative stress and inflammation." (PMID 37924679, 2023).
staphylococcus aureus infection (2 papers, 2019 to 2020). An infectious process in which the bacteria Staphylococcus aureus is present. "In addition, we found signaling pathways associated with inflammatory signal transduction and immune response were changed at protein level, including the staphylococcus aureus infection, HIF-1α and NF-kappa B signaling pathway." (PMID 32458987, 2020). "Researchers have shown that HIF-1a could contribute to response about Staphylococcus aureus infection in mast cell under hypoxia." (PMID 31281330, 2019).
streptococcal infection (2 papers, 2018 to 2025). Any of the several infectious disorders caused by members of streptococcus, a genus of gram positive bacteria belonging to the family Streptococcaceae. "There are follow up studies that demonstrated that HIF1α promotes myeloid cells (macrophages and/or neutrophils) pro-inflammatory activation and antimicrobial defense in a streptococcal infection model." (PMID 29483608, 2018). "For instance, HIF-1α plays a critical role in the immune response to Streptococcus infection, suggesting that HIF-1 activation may represent an adaptive response to infection." (PMID 41562069, 2025).
teratoma (2 papers, 2010 to 2023). A non-seminomatous germ cell tumor characterized by the presence of various tissues which correspond to the different germinal layers (endoderm, mesoderm, and ectoderm). "Deletion of Hif-1α in teratoma tumour models resulted in smaller tumours compared with teratomas containing wild-type Hif-1α." (PMID 20461086, 2010). "Based on our finding that exposure of pregnant dams to hypoxic conditions stabilized HIF-1α in both right and left gonads, we hypothesized that the systemic reduction of oxygen levels, would abolish the left-bias in teratoma incidence in 129/SvJ Dnd1Ter/+ mice." (PMID 37180974, 2023).
thymic tumor (2 papers, 2015 to 2019). "We aimed to analyze genotypes of VEGF-A, VEGFR2, Flt4, PDGFRα, HIF-1α and ERCC1 and their correlation with thymic tumor risk and patient outcome." (PMID 26254278, 2015). "PTEN-null thymic tumors expressed high levels of HIF1A and that increased further on AMPK deletion." (PMID 30995468, 2019).
urinary tract infection (2 papers, 2021 to 2022). "Experimental data supports that roxadustat may increase infection by upregulating HIF-1α and affecting adaptive immune responses, but we did not get the result that roxadustat will increase the infection, either upper respiratory or urinary tract infection." (PMID 36420092, 2022).
Varicose veins (2 papers, 2018 to 2023). Enlarged and tortuous veins. "First, the muscle cells of people with varicose veins show levels of the markers studied similar to normal cells subjected to hypoxia (Hif-1α, VEGF, TGF-β1, and eNOS)." (PMID 30498761, 2018).
xeroderma pigmentosum (2 papers, 2021 to 2023). Xeroderma pigmentosum (XP) is a rare genodermatosis characterized by extreme sensitivity to ultraviolet (UV)-induced changes in the skin and eyes, and multiple skin cancers. "In keratinocytes, HIF-1α transcriptionally activated several factors related to the nucleotide excision repair (NER) pathway, such as xeroderma pigmentosum (XP) group proteins." (PMID 36901857, 2023).
ZIKV infection (2 papers, 2020 to 2026). "Collectively, our findings unveil a novel mechanism underlying that ZIKV infection induces the expression of PTBP1 via the HIF-1α pathway." (PMID 42037413, 2026). "ZIKV infection upregulated HIF-1α expression, an adverse response that could be alleviated by FA treatments." (PMID 32392268, 2020).